EGFR (epidermal growth factor receptor)
Diseases named in the same sentence as EGFR in open-access papers (continued):
Sharing a sentence is not in itself a finding about the gene and the disease.
cancer (continued). "A correlation between nuclear EGFR expression, poor survival and chemo-radiation resistance has been in fact demonstrated in various types of cancer, including HNSCC." (PMID 36817764, 2023). "Suppression of GSDMD inhibited the activation of EGFR/Akt signal in cancer cells and impede their proliferation." (PMID 36161280, 2023). "The nuclear localization of EGFR has been shown to correlate with worse prognosis in an ever growing list of cancer including, breast, colorectal, ovarian, lung, oropharyngeal and laryngeal." (PMID 37720348, 2023). "Our findings here provide new impetus to develop new generations of target therapy for mutant EGFR-related human cancers in the future." (PMID 37333807, 2023). "Non-small-cell lung cancer (NSCLC) is a typical inflammation-associated cancer and epidermal growth factor (EGF) receptor (EGFR) mutations are the most common driver mutations of NSCLC." (PMID 37444399, 2023). "Although there have been many studies investigating inhibition of EGFR in CRC little is known regarding the dynamics of the EGFR pathway in human cancers." (PMID 36352028, 2023). "Although the effects of CL-387,785 on AD pathology (i.e., tau) and its mechanism of action require further investigation, CL-387,785 can be considered a potential EGFR TKI for both cancer and AD." (PMID 37601068, 2023). "Overall, the future directions of this study lie in leveraging these structural insights to advance the understanding of EGFR-related cancers and to develop more precise and effective therapeutic strategies." (PMID 38035047, 2023). "We present several case studies with varying stages of cancer development (I−III), mutation status (EGFR, ALK), and biomarker expression based on a three-gene panel (CD133, KRT19, and MUC1)." (PMID 36900350, 2023). "Gefitinib is a selected EGFR inhibitor that inhibits signal transduction to attenuate malignant neoplasm cell growth and proliferation." (PMID 36646686, 2023). "Supporting previous studies, in vivo and in vitro studies demonstrated that DT‐IgG suppresses cancer cell growth and has significant antiangiogenic effects by targeting EGFR and VEGF." (PMID 37042307, 2023). "CXCL1 increases the proliferation of OSCC cancer cells, which is associated with the activation of CXCR2 that transactivates epidermal growth factor receptor (EGFR)." (PMID 37408240, 2023). "Collectively, our research highlights an efficient personalized therapy via NRP1/EGFR signaling of malignant tumors." (PMID 37891570, 2023). "Inhibiting the production of HGFs in CAFs can induce the resensitization of cancer cells to gefitinib in EGFR‐mutant NSCLC persisters both in vivo or in vitro." (PMID 37638338, 2023). "Most administered adjuvant therapies were non-tyrosine kinase inhibitors (TKI) and were conventional, but a few patients who experienced cancer recurrence underwent EGFR testing and received TKI therapy." (PMID 36980320, 2023). "Nowadays, due to advances in molecular pathology, specific genomic alterations, such as epidermal growth factor receptor (EGFR) mutations, can provide additional diagnostic evidence to determine the origin of the cancer cells." (PMID 40733862, 2023). "Despite the lack of overlap in input gene signatures, all three DMEA analyses correctly identified EGFR inhibitors as the top toxic drug MOA for the EGFR inhibitor-sensitive cancer cell lines." (PMID 37226094, 2023). "eHSP90 has been observed to interact with several receptors and signaling pathways involved in cancer, including the EGFR, vascular endothelial growth factor receptor (VEGFR), and IGF-1R." (PMID 36902446, 2023).
cancer (continued). "Indeed, our findings partly support this conclusion that AnxA6 SUMOylation enhances gefitinib efficacy to reduce A431 cell growth and migration, which indicates that AnxA6 SUMOylation may be an underlying novel mechanism for the EGFR-TKI resistance in many cancers." (PMID 37528485, 2023). "Currently, there are two main therapeutic approaches that are effective for targeting EGFR in cancer: monoclonal antibodies and small-molecule tyrosine kinase inhibitors." (PMID 37315787, 2023). "As reported, chemotherapy or epidermal growth factor receptor (EGFR) kinase inhibitors improve the median survival of patients with advanced cancer, but the overall survival remains poor." (PMID 36827002, 2023). "One of the most commonly used approaches of active targeting is the targeting of overexpressed receptors on cancer cells, such as the epidermal growth factor receptor (EGFR) or the human epidermal growth factor receptor 2 (HER2)." (PMID 38140117, 2023). "Their presence in cancers such as colorectal cancer (CRC) is a well-defined diagnostic marker and indicates probable resistance to EGFR-inhibitor treatment." (PMID 37509339, 2023). "EGF is characterized by overexpression in various cancer cell types, and binding to its receptor EGFR triggers a series of important processes ultimately affecting cell growth, differentiation, and proliferation." (PMID 38027211, 2023). "The role of epidermal growth factor (EGF) signaling via its receptor in the plasma membrane (EGFR) in cancer cell proliferation is well known." (PMID 37834119, 2023). "In Lgr5+ intestinal stem cells (ISCs), YAP suppresses Wnt signaling, reprograming the cells to induce regenerative properties through EGFR signaling in line with cancer initiation." (PMID 37444578, 2023). "In contrast, erlotinib, which inhibits the epidermal growth factor receptor essential in cancer proliferation, was found to be more responsive in the low-risk category." (PMID 37547766, 2023). "For each cancer type they are indicated in, EGFR and ERBB2 consistently rank the highest both in terms of the fraction of cell lines they are essential in and the mean and median p(dependency) across cell lines." (PMID 37835579, 2023). "AXL signaling primarily promotes invasion, while EGFR signaling favors proliferation, and their interaction contributes to cancer metastasis." (PMID 37834326, 2023). "Anti-EGFR antibodies can be used to target NDEs to cancer cells, or they can be used to deliver drugs or other therapeutics to cancer cells." (PMID 37376417, 2023). "The pathways in which these core targets were enriched included EGFR tyrosine kinase inhibitor resistance, PI3K-Akt signalling pathway, ErbB signalling pathway, as well as pathways in cancer among others." (PMID 37099169, 2023). "Despite the pivotal role of epidermal growth factor receptor (EGFR) in cancer, little is known about the alternative cellular signaling for the proliferation and/or survival in the absence of EGFR." (PMID 37341071, 2023). "Epidermal growth factor receptor (EGFR) is another transmembrane glycoprotein that plays an important role in cancer treatment and wound healing, and it has numerous ligands for its activation." (PMID 37759771, 2023). "The emergence of cancer cell resistance due to EGFR pathway alterations was found in the majority of patients who received panitumumab plus trifluridine-tipiracil." (PMID 37200022, 2023). "It has been demonstrated that abnormal EGFR expression in cancer is in part due to dysregulated protein transport." (PMID 37542131, 2023). "EGFR overexpression has been shown to increase the radiosensitivity of various cancer types, and EGFRm+ NSCLC cell lines are highly radiosensitive in vitro." (PMID 38248726, 2023). "For instance, gefitinib (Iressa®) and erlotinib (Tarceva®) are 4-amino quinazoline derivatives that have been shown to exert their anti-cancer activity through the inhibition of epidermal growth factor receptor (EGFR)." (PMID 37513420, 2023).
cancer (continued). "There is, however, an extensive literature concerning treatment squamous cell carcinoma of the head and neck (SCCHN) showing that the EGFR directed monoclonal antibody cetuximab plus radiotherapy has significant activity in this EGFR-driven cancer." (PMID 37417890, 2023). "The binding between EGFR and its ligands activates a downstream signaling cascade that in turn promotes proliferation, differentiation, migration, and survival of cancer cells." (PMID 38077389, 2023). "Lung tumors, mainly non-small cell lung cancer (NSCLC), showed robust CD73 expression signatures among all cancer types, particularly when associated with common oncogenic drivers of NSCLC, such as mutant epidermal growth factor receptor (EGFR) and KRAS." (PMID 38067409, 2023). "GFT is used in the targeted therapy category due to its ability to block the epidermal growth factor receptor (EGFR), which is overexpressed in many types of cancer and promotes the growth and spread of cancer cells." (PMID 38004415, 2023). "A combination of EGFR-targeting agents with chemotherapy or radiotherapy has been developed to improve the effectiveness of cancer treatment and its application to various patient populations." (PMID 37438719, 2023). "Anti-cancer drugs targeting either EGFR or HER2 have been clinically approved, but the emergence of drug resistance is nearly inevitable." (PMID 37242487, 2023). "Our previous findings indicate that SEMA3C functions as a secreted soluble autocrine growth factor that drives cancer growth by transactivating multiple RTKs such as EGFR, HER2 and MET via Plexin B1." (PMID 37443749, 2023). "According to TCGA data, EGFRvIII is typically found in classical cancers where EGFR amplification is most prominent." (PMID 38201528, 2023). "Previous studies also reported that CD73 was positively correlated with EGFR expression and sustained cancer-stem-cell traits in HCC." (PMID 36899373, 2023). "For example, inhibition of the SRC/EGFR axis in combination with gemcitabine dramatically reduced cancer cell proliferation, survival, and the growth of orthotopic tumors." (PMID 37120696, 2023). "The conjugate was applied to three different human cancer cell lines, showing increased specificity and toxicity against cells expressing the EGFR." (PMID 36977072, 2023). "This hybrid early drug discovery screening strategy has the potential to yield a new generation of EGFR-TKIs based on natural cannabis products, suitable for cancer therapy." (PMID 37128337, 2023). "The epidermal growth factor receptor (EGFR) is a cell surface receptor and tyrosine kinase, which shows amplification and/or mutation in several types of cancers." (PMID 37182181, 2023). "Long‐term exposure to PM2.5 appeared to increase the proliferation of both EGFR wild‐type and EGFR mutant cancer cells (P < 0.05)." (PMID 36975376, 2023). "Numerous anti‐EGFR compounds, including tyrosine kinase inhibitors (TKIs) and monoclonal antibodies, have been developed and approved for different cancers." (PMID 36670542, 2023). "Firstly, co-expression of increased quantities of EGFR and their respective ligands results in a transformed cellular phenotype, in this context, cancer." (PMID 38090376, 2023). "The anti-HER2 antibody trastuzumab and the dual EGFR/HER2 kinase inhibitor lapatinib were used in a phase 2 trial performed at four Italian academic cancer centers; the results were as follows: ORR of 30%, DCR of 74%, with 22% of Grade 3 toxicity." (PMID 37324019, 2023). "Epidermal growth factor receptor (EGFR) is a common tyrosine kinase receptor that plays an important role in cancer." (PMID 37644107, 2023). "A range of small molecule inhibitors and monoclonal antibody therapies have been designed to target EGFR hyperactivation in cancers of epithelial origin." (PMID 37181747, 2023).
cancer (continued). "Epithelial tight junction integrity is also compromised by anti-cancer drugs such as epidermal growth factor receptor (EGFR)–tyrosine kinase inhibitors (TKIs), resulting in the onset of diarrhea." (PMID 37050295, 2023). "Based on these results, we conclude that LP-S is a promising probe for NIR imaging of cancers with high EGFR expression in future clinical applications." (PMID 37736720, 2023). "Abnormal or disrupted angiogenesis is considered to be one of the hallmarks of cancer, and an increasing interest in targeting EGFR and VEGFR pathways has been observed in clinical oncology." (PMID 36839989, 2023). "We used a specific AirID-fusion antibody for exPPI analysis of epidermal growth factor receptor (EGFR) in cancer cell lines." (PMID 38097606, 2023). "Current therapies approved by the Food and Drug Administration (FDA) for targeting EGFR in cancer include tyrosine kinase inhibitors and monoclonal antibodies." (PMID 38137520, 2023). "Highly proliferative cancer stem cells also express EGFR and can be inhibited by EGFR targeted TKIs." (PMID 37114134, 2023). "The broader activity of daunorubicin-EGFR inhibitor combinations is also evident from the pan-cancer analysis." (PMID 37629110, 2023). "Overexpression of EGFR, a growth factor receptor tyrosine kinase and/or its ligand, is common in many types of cancer and supports the growth of solid tumors." (PMID 38152616, 2023). "The results revealed the top three significantly enriched KEGG pathways, which were pathways in cancer (hsa05200), EGFR tyrosine kinase inhibitor resistance (hsa01521) and endocrine resistance (hsa01522)." (PMID 37446563, 2023). "The EGFR signaling cascade is a key regulating factor in cell proliferation, apoptosis, metastasis and angiogenesis, differentiation, division, survival, and cancer development." (PMID 37687164, 2023). "4.5.dianilinophthalimide is a selective inhibitor of the epidermal growth factor receptor signal transduction pathway which is essential for the growth and metastasis of various cancer cells." (PMID 37268878, 2023). "The epidermal growth factor receptor is often expressed at high levels in different cancers and its expression levels are positively correlated with cancer progression and poor prognosis." (PMID 37108294, 2023). "Epidermal growth factor receptor (EGFR) is a receptor kinase that is highly expressed in cancer cells." (PMID 37143400, 2023). "It has been shown that the overexpression of EGFR in MCF-7 cells provides cancer cells with resistance to Fulv, and the resistant phenotype can be reversed upon cotreatment with a combination of Fulv and the EGFR inhibitors, erlotinib or gefitinib." (PMID 37575061, 2023). "Recently, it was shown that EGFR possesses kinase-independent (KID) pro-survival functions in cancer cells." (PMID 37446288, 2023). "Another cancer-related pathway which was addressed after 12 h of AV25R exposure is the EGF/EGFR signaling pathway." (PMID 38138609, 2023). "First, we investigated the efficacy of the PAI-1 inhibitor SK-216 with EGFR-TKI-treatment-naive cancer cells." (PMID 36831438, 2023). "EGFR blockade often leads to oxidative stress increase in cancer cells, which, in turn, can drive cell death." (PMID 37723219, 2023). "PKP2 promotes the growth, division, and migration of cancer cells through activating the EGFR signaling pathway in LUAD cells." (PMID 37920207, 2023). "The two types of cancer cells were selected because of the reported high level of EGFR expression in both of them." (PMID 36676140, 2023). "No matter how NIR dye IR700DX conjugated with nanobodies that targeted a single epitope (7D12) or two epitopes (7D12-9G8) of EGFR, both of the complexes exhibited cell toxicity in EGFR-overexpressing cancer cells when exposed to light (only)." (PMID 38067344, 2023). "Future work into the plausibility of EGFR-induced matriptase activation, particularly in EGFR-dependent cancers such lung, should follow." (PMID 36716335, 2023).
cancer (continued). "Inappropriate activation of EGFR in cancer can also originate from the changes occurring in other genes involved in receptor endocytosis and recycling." (PMID 37766136, 2023). "Recently, efforts have been made to fight resistance by targeting EGFR and DNA using “combi-molecules” (designed to aim at two targets in cancer cells)." (PMID 37182181, 2023). "This approach has the potential to be used as a therapeutic cancer treatment against tumours in which EGFR is overexpressed." (PMID 36840363, 2023). "Epidermal growth factor receptor (EGFR) is a member of the receptor tyrosine kinases (RTKs) family, which is an important targeted therapy in cancer treatment." (PMID 36770659, 2023). "Common palmitoylated proteins in different cancer types are EGFR, RAS (KRAS4A, NRAS), CD82 tetraspanin, CD44, PD-L1, and CKAP4." (PMID 36671802, 2023). "Inhibiting the tyrosine kinase activity of epidermal growth factor receptor (EGFR) using small-molecule tyrosine kinase inhibitors (TKIs) or monoclonal antibodies is often ineffective in treating cancers harboring wild-type EGFR." (PMID 37762316, 2023). "For example, one of the most used targets with this mechanism was the receptor for the epidermal growth factor (EGFR), which can be overexpressed in different types of cancer, such as colon, neck, and head, ovary, and lung, among others." (PMID 37371712, 2023). "M2 macrophages release high concentrations of epidermal growth factor (EGF) and induce angiogenesis and the invasion and metastasis of cancer cells through the activation of an EGF receptor (EGFR)." (PMID 36831623, 2023). "Cancer markers, such as KRAS G12D, EGFR L858R, and EGFR T790M mutations, containing 0.1% VAF, were clearly detected in under 2 h with a high reliability comparable with that of ddPCR." (PMID 36979592, 2023). "EGFR targeting is prominent in cancer treatment, with TKIs and monoclonal antibodies designed to disrupt signaling and reduce proliferation." (PMID 37764362, 2023). "Decreased PHLDA2 expression increases cell proliferation and reduces sensitivity to targeted agents in EGFR/ErbB2-driven cancer." (PMID 37575253, 2023). "Autophagy can differentially regulate the different breast CSCs through TGFβ/Smad and EGFR/Stat3 signaling, thereby limiting cancer growth." (PMID 37422448, 2023). "Cancers have spread widely as a result of genetic changes that occurred in aberrant EGFR activity that has been reported to be involved in the development of many human cancers." (PMID 37513936, 2023). "In line with this, whole-genome CRISPR screening identified FGFR1 as the top target promoting survival of mesenchymal EGFR mutant cancers." (PMID 37894376, 2023). "Although numerous reviews have discussed EGFR as a target in cancer, inflammatory diseases, and monogenic diseases, the regulation of EGFR expression or signaling as a multi-disease target requires further investigation." (PMID 37601068, 2023). "The developed therapeutic approach 7D12NK cells demonstrated active targeting toward EGFR overexpressed cancer cells." (PMID 37344853, 2023). "Studies have examined the use of EGFR peptide ligands as promising tools for the targeting of overexpressed EGFR receptors in different cancer cell types." (PMID 37243023, 2023). "In normal cells, low EGFR levels were recorded; on the contrary, higher levels were detected in many cancer types as lung, breast, esophagus and colon cancers." (PMID 37298747, 2023). "Overall, our results indicate that rCAFs mediate cancer cell chemoresistance via the TGFα-EGFR paracrine signaling." (PMID 37821657, 2023). "Multivariate analysis used for evaluating the association of SCR with variables revealed that the number of designated cancer hospitals and radiation therapies were independent factors associated with the SCR of EGFR-TKIs." (PMID 36997606, 2023). "JNK signalling, p38‐MAPK signalling and PI3K‐AKT signalling are classical downstream signalling pathways of EGFR that play important roles in cancer progression." (PMID 37132043, 2023).